CD79A (CD79a molecule)
Description:
Required in cooperation with CD79B for initiation of the signal transduction cascade activated by binding of antigen to the B-cell antigen receptor complex (BCR) which leads to internalization of the complex, trafficking to late endosomes and antigen presentation. Also required for BCR surface expression and for efficient differentiation of pro- and pre-B-cells. Stimulates SYK autophosphorylation and activation. Binds to BLNK, bringing BLNK into proximity with SYK and allowing SYK to phosphorylate BLNK. Also interacts with and increases activity of some Src-family tyrosine kinases. Represses BCR signaling during development of immature B-cells.
Synonyms: IGA; MB1; MB-1; Ig-alpha; IGAlpha
Tractability: Antibody: its Gene Ontology location is reachable by antibodies, with high confidence; UniProt places it where antibodies can reach, with medium confidence; UniProt predicts a signal peptide or a membrane-spanning region. PROTAC: ubiquitination databases record sites on it.
Gene: Protein-coding gene on chromosome 19 (41,877,279 to 41,881,372, forward strand). Ensembl gene ENSG00000105369.
Subcellular location: Cell membrane
Pathways (Reactome):
Immune System: Antigen activates B Cell Receptor (BCR) leading to generation of second messengers; CD22 mediated BCR regulation
Disease: Potential therapeutics for SARS
Gene Ontology:
Molecular function: identical protein binding; protein binding; transmembrane signaling receptor activity
Biological process: B cell activation; B cell differentiation; B cell proliferation; B cell receptor signaling pathway; cell surface receptor signaling pathway
Cellular component: B cell receptor complex; IgM B cell receptor complex; plasma membrane; external side of plasma membrane; membrane raft; multivesicular body; membrane
Genetic constraint (gnomAD): Loss-of-function variants: 14 observed, 22.09 expected, observed/expected ratio (o/e) 0.63, 90% interval 0.42 to 0.99. The upper end of that interval is the gene's LOEUF score, 0.99, which puts it in group 4 of 6, group 1 being the genes least tolerant of losing a copy. Missense variants: 230 observed, 284.41 expected, observed/expected ratio (o/e) 0.81, 90% interval 0.73 to 0.9. Synonymous variants: 109 observed, 123.76 expected, observed/expected ratio (o/e) 0.88, 90% interval 0.75 to 1.03.
Gene-disease validity (ClinGen):
ClinGen rates the evidence that CD79A causes each of these diseases.
agammaglobulinemia 3, autosomal recessive (autosomal recessive): Definitive.
Cancer hallmarks: proliferative signalling (promotes); invasion and metastasis (promotes)
Homologues: Orthologues: chimpanzee CD79A (99% identical), macaque CD79A (90% identical), dog CD79A (76% identical), guinea pig CD79A (75% identical), rat Cd79a (70% identical), mouse Cd79a (69% identical), pig CD79A (66% identical), tropical clawed frog cd79a (39% identical), zebrafish cd79a (27% identical). Paralogues in human: CD79B (25% identical).
Diseases named in the same sentence as CD79A in open-access papers:
CD79A is named in the same sentence as 1,066 diseases in open-access papers, as found by Europe PMC text mining. Sharing a sentence is not in itself a finding about the gene and the disease. The quoted sentences say what the papers report.
COVID-19 (829 papers, 2020 to 2026). A disease caused by infection with severe acute respiratory syndrome coronavirus 2. "We also noticed a remarkable change towards a negative correlation of microRNA137 expression with CD1a, CD11c and CD79a in COVID-19-positive AML patients." (PMID 38902412, 2024). "Especially a new population appeared in COVID-19 groups (Cluster 5), which highly expresses B cell-related genes, such as CD79A and MS4A1." (PMID 37446049, 2023). "Performing this analysis for the COVID-19 patients demonstrated clear B- and T-cell clusters, defined by expression of TCF7, LEF1 (clusters 0 and 1), CD74, CD79A (clusters 2 and 3), IL7R (cluster 4) and CCL5, NKG7, GNLY (cluster 6)." (PMID 33884369, 2021).
primary immunodeficiency (221 papers, 2005 to 2026). "Functional annotation of KEGG pathway enrichment analysis revealed changes related to primary immunodeficiency in the BALF of severe MPP children, which was associated with the down-regulation of CD19, TNFRSF13C, CD79A, and AICDA genes." (PMID 28302172, 2017). "Among the remaining ones, it is of note the gene set linked to primary immunodeficiency given that it includes genes related to CLL biology such as Zap70, CD19, BTK and CD79A genes." (PMID 27611921, 2016). "GSEA analysis adds more insight into the 23 ERBB2-related DEGs and primary immunodeficiency signaling pathway, showing that ERBB2-related DEGs associated with primary immunodeficiency were mainly down-regulated ERBB2-related DEGs, such as CD79A, CD19, CD3D, CD3E, CD8A, and CD4." (PMID 36437939, 2022). "An equally high overrepresentation (OVF = 20.83, q-value = 2.38 × 10−6) was determined for the “magenta” module that was enriched in genes that control primary immunodeficiency, including ADA, CD19, CD79A, IGLL1, TAP1, TAP2, TNFRSF13C, and ZAP70." (PMID 32873298, 2020). "In the current study, KEGG pathway enrichment analyses have revealed changes related to primary immunodeficiency in severe MPP patients, which involves CD79A, AICDA, CD19, and TNFRSF13C genes." (PMID 28302172, 2017). "Notably, CD79A and IL7R were involved in the primary immunodeficiency pathway (FDR = 1.43 × 10−3), which represents essential disruptions in adaptive immune cell development and function." (PMID 40725191, 2025).
Immunodeficiency (179 papers, 2004 to 2026). Failure of the immune system to protect the body adequately from infection, due to the absence or insufficiency of some component process or substance. "Genetically defined immunodeficiencies were first described with the identification of BTK mutations in X-linked (Bruton’s) agammaglobulinemia, and subsequently expanded to include several B-cell receptor genes, including BLNK, μ heavy chain, and CD79A/B5,38." (PMID 31409799, 2019).
systemic lupus erythematosus (176 papers, 2006 to 2026). An autoimmune multi-organ disease typically associated with vasculopathy and autoantibody production. "This is illustrated by the overexpression of CD79a and CD79b, molecules involved in the transduction of BCR signal, and of CD81 whose co-expression with BAFFR and CD38 in transitional B-cells is associated with active systemic lupus erythematosus." (PMID 39185406, 2024). "In addition, CD79A represents an effective inhibitor target for human B cell activation, rendering it a promising therapeutic option for autoimmune diseases such as systemic lupus erythematosus and collagen-induced arthritis." (PMID 39664749, 2024).
autoimmune disease (172 papers, 2003 to 2026). A disorder resulting from loss of function or tissue destruction of an organ or multiple organs, arising from humoral or cellular immune responses of the individual to their own tissue constituents. "Furthermore, ITGAX is considered a risk gene in autoimmune diseases, and synovial CD79a-positive B cells may be a helpful biomarker of histologic disease activities in RA." (PMID 39315289, 2024).
colitis (158 papers, 2012 to 2026). Inflammation of the colon. "Compared to control mice (Cd79a−/− mice that received PBS), Cd79a−/− mice that received B cells from Itgam+/+ mice exhibited less severe colitis." (PMID 34804004, 2021). "Cd79a−/− mice that received Itgam−/− B cells developed severe colitis similar to that in control mice, as measured by body weight loss, DAI score, and histological score." (PMID 34804004, 2021). "To explore the impact of EGCG treatment on the intestinal microenvironment in colitis, we performed a comprehensive analysis of various immune cells, including CD4+ T, CD8αβ+ T, CD79a+ B cells, and F4/80+ macrophages, using flow cytometry." (PMID 39116526, 2024). "Importantly, adoptive transfer (AT) of Peyer’s patches (PP)-derived wild-type (WT) B cells, but not Itgam−/− (CD11b KO) B cells, inhibited colitis in Cd79a−/− B cell-deficient mice, suggesting that CD11b is indispensable for the regulatory function of GALT B cells." (PMID 34804004, 2021).
myeloma (148 papers, 2008 to 2025). "SMM patients with an evolving pattern of the M-protein showed an increase in genes associated to myeloma (SLAMF7, CD79A, CD79B) and AXL." (PMID 34880879, 2021). "Frequent downregulation or deletion of CD79A could be potential clues for the diagnosis of plasma cell myeloma in the elderly." (PMID 36561317, 2022). "Transcriptomic analysis in a panel of 31 myeloma cell lines and 25 patient samples showed an enrichment of specific B-cell genes and specific B cell surface markers, including CD20 and CD79A in venetoclax- sensitive myeloma cells." (PMID 36387095, 2022).
hypogammaglobulinemia (146 papers, 2004 to 2025). "We present a patient previously diagnosed with agammaglobulinemia due to CD79A (Igα) deficiency revealing a novel pathogenic insertion variant in the CD79a gene (NM_001783.3:c.353_354insT)." (PMID 29335801, 2018). "Here, we describe a 16-year-old male, who was diagnosed with agammaglobulinemia associated with CD79a deficiency at 2 years of age." (PMID 29335801, 2018). "Agammaglobulinemia with other inherited pattern were also concluded: AR agammaglobulinemia was associated with mutations in several other genes such as IGHM, IGLL1, CD79A, CD79B, BLNK, PIK3R1, and TCF3 genes; AD-related agammaglobulinemia was also found with LRRC8A and TCF3 gene mutations." (PMID 36140582, 2022). "In view of this patient’s clinical presentation and agammaglobulinemia, the differential diagnosis includes autosomal recessive forms of the disease (such as defects in IGHM, IGLL1, CD79A/B, PIK3R1, PIK3CD), as well as, more rarely, XLA." (PMID 41327272, 2025).
respiratory infections (104 papers, 2010 to 2026). "Among these genes, CD79A is associated with autosomal recessive agammaglobulinemia 3 [OMIM: 613501] that is clinically characterized by adult‐onset recurrent respiratory infections, decreased immunoglobulins, decreased number of mature B cells, and normal T cell numbers." (PMID 32073752, 2020).
Autoimmunity (101 papers, 2011 to 2026). The occurrence of an immune reaction against the organism's own cells or tissues. "For example, anti-CD79A antibody therapy was shown to enhance immune system recovery against autoimmunity." (PMID 31178673, 2019).
lymphoma (86 papers, 1979 to 2025). A malignant (clonal) proliferation of B- lymphocytes or T- lymphocytes which involves the lymph nodes, bone marrow and/or extranodal sites. "On the other hand, genetic studies provided insights into the contribution of CD79a and CD79b (and their mutations) towards tumorigenesis and lymphoma development." (PMID 38203179, 2023). "However, within the pathologically active BCR signaling in lymphoma, CD79A or CD79B mutations cannot be considered separately from other mutations." (PMID 38203179, 2023). "Moreover, KLHL14 (Kelch-Like Family Member 14, a tumor-suppressing chaperone regulating protein folding, frequently mutated in lymphomas) promotes CD79a and CD79b ubiquitination and their consequent downregulation." (PMID 38203179, 2023). "Due to its specificity for B cells, CD79a is commonly used as a marker in immuno-histochemistry to identify and study B cell-related disorders, such as lymphomas and leukemias." (PMID 41040928, 2025). "The markers that differentiate these entities include lymphoma markers (e. g., cluster of differentiation [CD] 20, CD79a, BCL2, CD10, BCL6, multiple myeloma oncogene), while in HT, epithelial markers, such as cytokeratin are positive." (PMID 40937371, 2025). "The main example of uneven distribution of CD79A and CD79B mutations between lymphoma subtypes is DLBCL." (PMID 38203179, 2023). "As an example of this complexity, CD79A and CD79B mutations were included in a large network of 153 lymphoma-altered genes related to NF-κB signaling." (PMID 38203179, 2023). "The evaluation of the genes in association with BCR has revealed that targeting CD79A, CD79B, and LAMTOR4 as the shared genes can provide novel biomarkers for pSS progression into lymphoma." (PMID 37176092, 2023). "CD79b (and CD79a) serves as critical signaling components of the B‐cell receptor that promotes lymphoma survival." (PMID 37206291, 2023). "We confirmed that EBNA2 was a negative regulator of CD79A and CD79B in both LCL and lymphoma cell backgrounds and we also showed reduced CD79A and CD79B protein levels in response to EBNA2 activation in LCLs." (PMID 36383217, 2022). "Another B cell marker, CD79a, may also be expressed in a minority of cases (10%) of T-lymphoblastic leukemia/lymphoma." (PMID 40227608, 2025). "However, more studies are necessary to elucidate the exact contribution of either CD79a or CD79b (and their mutations) to various types and states of BCR signaling in lymphoma." (PMID 38203179, 2023). "Importantly, CD19-negative or -low leukemia or lymphoma cells retain expression of other B cell markers such as CD22 for B-ALL, CD20 and CD79a for lymphoma." (PMID 34809678, 2021). "Immunohistochemical analysis revealed that large cells in the germinal centers and lymphocytes in the perifollicular/marginal zone were positive for the pan-B-cell antigens CD20 and CD79a and positive for Bcl-2, also supporting the neoplastic nature of this lymphoma lesion." (PMID 31439011, 2019). "Based on the criteria defined by WHO classification of tumors of haematopoietic and lymphoid tissues, MALT lymphoma is a lymphoma composed predominantly of small cells with CD20-positive, CD79a-positive and expression of marginal zone cell-associated antigens CD21 and CD35." (PMID 26376733, 2015). "In addition, CD79B transcripts are significantly more abundant than CD79A (fourfold increase) in some lymphoid cancer cell lines, suggesting that CD79B could act as a putative tumor promoter in leukemic B-cells." (PMID 40232347, 2025). "Notably, in all lymphoma cases, CD79a expression was detected by IHC staining." (PMID 39682155, 2024). "Furthermore, lymphoma sequencing studies revealed that the network of concurrently mutated genes in MCD DLBCL cluster includes inactivating mutations of KLHL14, which promotes My-T-BCR-dependent NF-κB signaling via reduction of CD79a and CD79b ubiquitination." (PMID 38203179, 2023).
lymphoma (continued). "B-lymphoblastic leukemia/lymphoma is characteristically positive for B cell markers, including CD19, CD79a, and CD22, which can all be assessed by flow cytometric analysis." (PMID 40227608, 2025). "Cluster 1 (top right) included genes such as CD79A, PTPRC, EZH2, MMP9, IKBKB, or CASP8, which were upregulated in GCB lymphomas (top right colored in orange)." (PMID 41472741, 2025). "The EVs markers; Tsg101 and CD63, and the lymphoma markers; CD45, CD79a, CD21, were detected in all EV samples." (PMID 36125986, 2022). "The EVs markers TSG 101, CD63 and lymphoma markers CD45, CD79a, CD21 were detected in patients with DLBCLs (L) and healthy dogs (C), CD20 was detected in one patient with DLBCL." (PMID 36125986, 2022). "Microscopic findings showed that the tumor was a hepatic MALT lymphoma, and immunohistochemical analysis revealed that the lymphoma cells were CD20+, CD79a+, BCL-2+, CD3−, and CD5−." (PMID 28353562, 2017). "The lymphoma cells displayed a CD3ε/CD56/TIA-1/granzyme-B/Perforin-positive and CD20/CD79a/CD4/CD8-negative immunophenotype and positive for Epstein-Barr virus by EBER in situ hybridization." (PMID 24886075, 2014). "A case of lymphoma of T-cell derivation with aberrant expression of three B-cell lineage markers (CD19, CD20, and CD79a), which was diagnosed on a left axillary excision, is described." (PMID 24066244, 2013). "Immunostains for CD20, CD79a, and PAX-5 showed strong positive staining of the atypical cells, confirming B-cell origin and resulting in the diagnosis of lymphoma, large B-cell type." (PMID 29147306, 2012). "As is common in the histological evaluation of canine lymphoma for routine diagnosis, immunophenotyping was restricted to the use of CD3 and CD79a cell markers." (PMID 14562028, 2003). "Immunohistochemistry for AE1/AE3, CD3 and CD79a were also negative, rendering carcinoma and lymphoma unlikely." (PMID 39402168, 2025). "MALT lymphomas typically express CD20, CD79a, and other B-cell markers while lacking T-cell markers and high-grade lymphoma features." (PMID 40491619, 2025). "In addition, new analysis predicted lymphoma subtypes using cell-of-origin markers that hematopathologists use in the clinical routine, including CD3, CD5, CD19, CD79A, MS4A1 (CD20), MME (CD10), BCL6, IRF4 (MUM-1), BCL2, SOX11, MNDA, and FCRL4 (IRTA1)." (PMID 38745770, 2024). "It is ITAM-dependent, can occur even in the absence of other BCR components (IgM and CD79a), and is considered an alternative lymphoma survival supporting mechanism." (PMID 38203179, 2023). "Clinicopathological data showed that CD79a-negative expression was observed in patients with decreased platelet numbers or with high-grade lymphoma." (PMID 36358798, 2022). "Expression of CD20 in lymphoma tissue could be detected in all patients by immunohistochemical analyses, while only 9% expressed CD5, 55% CD10, 9% CD30, 18% CD79a, 9% CD138, 82% BCL2, 55% BCL6 and 36% MUM1." (PMID 30340554, 2018). "In our patient, immunohistochemical analysis for lymphoma revealed positive immunostaining for CD79a, CD20, and cyclin D1, but there was no immunostaining for CD10 or CD23." (PMID 28705174, 2017). "Laboratory investigations revealed a recurrence of a low-grade lymphoma (CD79a+ and CD20−) without monoclonal gammopathy in the serum." (PMID 25621682, 2015). "The diagnosis of CD-20 negative lymphomas requires pathologists to use a comprehensive panel of markers in order to identify B-cell lineage and reflect various stages of B-cell differentiation, including staining for CD79a, CD19, and PAX5." (PMID 40612965, 2025). "Notably, CD79a expression indicates its utility as an adjunct to CD20, potentially compensating for its diminished expression owing to the plasmacytic differentiation of lymphoma cells or prior rituximab therapy." (PMID 38895050, 2024).